TNF (tumor necrosis factor)
Diseases named in the same sentence as TNF in open-access papers (continued):
Sharing a sentence is not in itself a finding about the gene and the disease.
cancer (continued). "We first revealed that an NEDD8-activating enzyme inhibitor exhibits an inhibitory effect on the TNF-α-induced activity of MMP9 in ESCC cells and therefore suppresses MMP9-dependent cancer cell migration." (PMID 33572115, 2021). "TNF-α is also able to induce EMT via p38 MAPK activation, and TNF-α-induced EMT has been related to the induction of cancer stem cells (CSCs)." (PMID 35047997, 2021). "Considering this refined view of TNF-α functions, several studies have focused on sensitizing cancer cells to TNFR1-induced apoptosis, for example by inhibiting survival signals, such as NF-κB, in combined therapy with TNF-α." (PMID 34712661, 2021). "Various pro-inflammatory cytokines such as tumor necrosis factor -α (TNF-α), IL-6, IL-8, interferon (IFN) γ, and macrophage migratory factor (MIF) have an important role in cancer cachexia." (PMID 34371835, 2021). "Therefore, a therapeutic approach that results in the degradation of cIAPs and/or antagonism of XIAP (X-linked inhibitor of apoptosis) could promote the lethal effects of TNF on cancer cells, while shutting down the survival pathway mediated by TNF driven NF-κB expression." (PMID 34572737, 2021). "TNF-α triggers the expression of the FAT10 gene via the TNF receptor 1, inducing the inflammatory signalling pathway of NF-κB in cancer cell lines." (PMID 34571823, 2021). "We detected higher levels of TNFα, IL-1Rα, MCP-1, IL-8, IL-10 and IL-17 in the plasma of cancer patients." (PMID 34950660, 2021). "The usefulness of anti-inflammatory cytokine therapies such as anti-TNFα therapy, anti-IL6 therapy, and anti-IL1α therapy on cancer cachexia have been reported." (PMID 34445197, 2021). "By producing interferon-gamma (IFN-γ), tumor necrosis factor-alpha (TNF-α), and granzymes, CTLs can destroy virus-infected cells and cancer cells." (PMID 34208346, 2021). "Caspase-8 activated by TNF-α cleaves GSDMC at it linker, liberating the GSDMC N-terminal domain to trigger pyroptosis in cancer cells." (PMID 33941231, 2021). "We selected the eleven cytokines that were significantly increased in cancer (GMCSF, IL-6, IL-1β, Rantes/CCL5, MIP1α, MIP1β, TNFα, MCP1/CCL2, IL-8, IL-12p40, IL10) and selected all the positive Pearson's correlations with r > 0.8 and significance of p < 0.01." (PMID 35048057, 2021). "Cancer cells express protocadherin 7 (PCDH7), promote carcinoma-astrocyte gap junctions, which then induces IFNα and TNF production and activation of STAT1 and NF-κB pathways in cancer cells to support brain metastasis." (PMID 33442395, 2021). "TNF-α, IL-6, and TGF-β are inflammatory cytokines that participate in both the initiation and progression of cancer." (PMID 33567693, 2021). "Regardless of the specific metabolic control exerted over cancer cells by inflammatory factors during PC, TNF-α, IL6, TGF-β, and IL10 are shared mediators for the initiation and progression of several cancer types." (PMID 34205944, 2021). "In summary, the levels of TNF-α and IFN-γ produced by anti-MUC1-CAR4 T cells were related to MUC1 expression on the cancer cell membrane." (PMID 33737613, 2021). "Further linking proinflammatory functions of NF-κB, O-GlcNAcylation and cancer, Ser-395 O-GlcNAcylation of TAB1 is required for NF-κB activation and expression of IL-6 and TNF-α." (PMID 34722537, 2021). "Other effector molecules being releases by the CTLs, such as interferon‐γ (IFN‐γ) and tumor necrosis factor α (TNF‐α), augment their cytotoxicity toward cancer cells." (PMID 34084145, 2021). "CH13L1 promotes inflammatory cytokine production (including TNF-α, IL-1β, IL-6, and IFN-γ), connective tissue growth, fibrosis, and cancer proliferation." (PMID 33498689, 2021).
cancer (continued). "Intestinal transcriptome analysis showed that mice treated with cancer therapeutics and B. bre JCM92 showed significantly enriched E2F targets, TNF-α signaling via NFκB, inflammatory responses, and IFN-γ responses." (PMID 33668827, 2021). "The pro-tumorigenic role of TNF-α in the progression to cancer under chronic inflammatory conditions was demonstrated in CAC mouse models, in which treatment with anti-TNF-α antibodies decreased both inflammation and the number of intestinal carcinomas." (PMID 34884543, 2021). "Some studies have shown that E3330 decreases the expression of inflammatory modulators, such as tumor necrosis factor-α (TNF-α) and interleukin IL-8, and inhibits the growth and migration of cancer cells." (PMID 34616737, 2021). "Studies found that SMC3 activates nuclear factor-κB (NF-κB) through autocrine tumor necrosis factor-α (TNF-α), which inhibits apoptosis in cancer cells." (PMID 34123852, 2021). "This was followed by development of the gold standard cytokine cocktail comprising IL‐1β, IL‐6, TNFα, and PGE2, as maturation signals for DCs;93, 94 however, MoDCs derived using this cocktail proved ineffective for cancer immunotherapy." (PMID 32663904, 2021). "The incredibly wide range of physiological functions dependent on TNF-α/TNFR1 in all body systems, including cancer immunosurveillance, render targeting this pathway highly challenging." (PMID 34712661, 2021). "CD40 is a member of the tumor necrosis factor (TNF) family and is a new immune‐modulating target with great potential in cancer treatment." (PMID 34184409, 2021). "crispa significantly enriched the genes of the five pathways (TNF/IL-17/MAPK/NF-kappa B signaling pathway, Transcriptional misregulation in cancer)." (PMID 34490085, 2021). "In vitro studies with the use of human NIMBC cancer cell lines showed that BCG increases the production of IL-6 and IL-8, GM-CSF (granulocyte-macrophage colony-stimulating factor), and TNF." (PMID 34361097, 2021). "Regulates cancer cells' survival, growth, and invasion through producing tissue remodeling molecules, including MMP-2, 9, TNF-α, CXCL10, and IL-1β.Protects cancer cells from cytotoxic effects of radiotherapy and anticancer agents." (PMID 35096289, 2021). "The pro-inflammatory cytokines, such as tumor necrosis factor-α (TNF-α), interleukine-6 (IL-6), and interleukine-1 (IL-1), have long been considered as mediators of cancer-induced muscle atrophy." (PMID 34199575, 2021). "Combining cancer immunotherapy with the IAP‐antagonizing activity of SM to enhance TNF‐ and TRAIL‐mediated cancer cell killing via cytotoxic lymphocytes is therefore a reasonable therapeutic approach." (PMID 33484626, 2021). "Of note, VAMP3 has been reported to be involved in CXCL6 and TNF-α release from the synovial sarcoma cell line SW982, indicating an active role of VAMP proteins in diffusible mediator secretion from cancer cells." (PMID 34567000, 2021). "Macrophages co-cultured with cancer cells showed significant upregulation (50- to 500-fold increase) of a variety of genes, such as CCL2, TNF- α, VEGF-C, and CSF-1, among many others." (PMID 34503128, 2021). "TNFα or TRAIL combinations and TNF-inducing chemotherapies sensitize some resistant cancers to SMAC mimetics." (PMID 34073507, 2021). "Exosomes released from cancer, when subjected to hypoxic conditions contain enhanced TGF-β, tumor necrosis factor alpha (TNF-α), and IL-6 cytokines levels." (PMID 34575889, 2021). "Specific flavonoids can attenuate the TNF-α-induced release of MCP-1/CCL2 and various recruiting cytokines from cancer cells." (PMID 34950252, 2021). "Inflammatory factors such as interleukin-6 (IL-6), tumor necrosis factor (TNF)-α, and leukemia inhibitory factor (LIF) are commonly examined for their roles in cancer-induced muscle wasting." (PMID 34395422, 2021).
cancer (continued). "In high concentrations, TNFα is able to eliminate methylcolanthrene (MCA)-induced sarcomas, as first described by Carswell, and approximately 28% of cancers are sensitive to sTNFα." (PMID 33540543, 2021). "Tumor necrosis factor-alpha (TNF-α), a prognosticator of cachexia, has been shown to regulate Notch signaling within cancer development and metastasis." (PMID 34886282, 2021). "High expression levels of IAP contribute to TNF and TRAIL resistance in cancer cells and consequently attenuate the impact of cancer immunotherapy." (PMID 33484626, 2021). "In HCC, infiltrating M2-TAM-derived TNFα promotes EMT and cancer stemness via the Wnt/β-catenin signaling pathway." (PMID 33406733, 2021). "TNF-α belongs to the TNF/TNFR superfamily and is considered to be one of the most promising anti-cancer factors." (PMID 34388989, 2021). "Recent research showed that chemokines and cytokines, namely, TNF-α, IL-6, and chemokine (C-C motif) ligand 2 (CCL2), have roles in the formation of the cancer microenvironment and are responsible for the migration of inflammatory cells and cancer cells." (PMID 34631699, 2021). "m6A-C2 cluster is distinguished by cancer and immune surveillance, involving epithelial mesenchymal transition, TGF-β signal, TNF-α signaling via NF-κB, and IL2/STAT5 signaling." (PMID 34993195, 2021). "TH1 activation induces the generation of IL-2, IL-12, IFN-γ, TNF-α and TNF-β and leads to the activation of cytotoxic CD8+ T lymphocytes, which destroy cancer cells." (PMID 33923108, 2021). "The increased levels of TNF-α and IL-6 in NMSC patients can be introduced as an epiphenomenon of a complex cancer-induced cytokine cascade." (PMID 33461943, 2021). "However, long-term surveillance and monitoring of patients on anti-TNFα treatment via data registries and long-term epidemiological studies are necessary to capture any long-term complications, particularly the development of cancers that can occur long after the follow-up time of RCTs." (PMID 34790122, 2021). "The major molecular targets of curcumin that help in cancer cell death are cyclooxygenase-2 (COX-2), nuclear factor kappa B (NF-kB), tumor necrosis factor-alpha (TNF-a), and cyclin D1." (PMID 34573087, 2021). "The top 20 significantly enriched pathways contained pathways in cancer, HIF-1 signaling pathway, PI3K-AKT signaling pathway, TNF signaling pathway, VEGF signaling pathway and Ras signaling pathway." (PMID 34177580, 2021). "Cancer pathway, PI3K-Akt signaling pathway, proteoglycan in cancer, hypoxia-inducible factor-1(HIF-1) signaling pathway, and tumor necrosis factor signaling pathway are included." (PMID 34593896, 2021). "Such an effect is more pronounced when FC2 is administered in combination with TNF or with the Smac-mimetic SM83 (namely 9a) in two out of three cancer cell lines tested." (PMID 34938412, 2021). "When we co-cultured ROR1-specific CAR T cells with ROR1-expressing K562 human cancer cells, we found that pentanoate-pretreated cells elevated the production of CTL-related cytokines IFN-γ and TNF-α." (PMID 34210970, 2021). "These genes are related to PD-L1 expression and PD-1 checkpoint in cancer, MAPK signaling, apoptosis, and TNF pathways; hence, they regulate the development, progression, and immune escape of cancer." (PMID 33440868, 2021). "Inflammatory cytokines such as TNF-α, IL-6, TGF-β, and IL-10, have been shown to participate in cancer initiation and progression, depending on the balance of pro- and anti-inflammatory cytokines and their relative abundance." (PMID 33466674, 2021). "Our profiles of eRNA expression from GR binding sites agree with reports from BEAS-2B epithelial cells stimulated with TNFα and Dexamethasone, and from A549 and U2OS cancer cell lines." (PMID 35011590, 2021).
cancer (continued). "The elevated levels of various cytokines, including TNF-α, IL8 and IL6, have been found in the serum of cancer patients treated with gemcitabine." (PMID 34771621, 2021). "Core cancer signaling pathways mediated by KRAS, TNF-alpha and JAK/STAT proteins were also found near the very top of the list." (PMID 34368836, 2021). "TAMs can induce EMT and stemness of cancer cells and related treatment resistance by the secretion of Wnt proteins, TGF-β, IL-6, IL-10 and TNFα." (PMID 34322664, 2021). "In the present study, we also observed that the pro-inflammatory cytokines that promote cancer progression, namely, IFN-γ, TNF-α, IL-1β, IL-6, IL-8, and IL-12, were decreased." (PMID 33869169, 2021). "The results of the study showed us the TNF-α/NF-κB/Twist1 signaling pathway was related to apoptosis, invasion, metastasis and EMT in cancer cells." (PMID 33854637, 2021). "The main KEGG pathways were TNF signaling pathway, NOD-like receptor signaling pathway, Cytokine-cytokine receptor interaction, Pathways in cancer, and necroptosis." (PMID 34592898, 2021). "For example, TNF-α expression was found to be higher in patients with stage III and IV cancer than in those with stage I and stage II cancer." (PMID 33578830, 2021). "Several inflammatory mediators, such as TNF-α, IL-6, TGF-β, and IL-10, have been shown to play a role in cancer progression." (PMID 34485118, 2021). "PM-induced oxidative stress has been accepted as a key molecular mechanism of many inflammatory modulators, such as tumor necrosis factor-α (TNF-α), interleukins IL-1, IL-6, IL-8, and COX-2, including MMP-9 expression and cancer cell metastasis." (PMID 34439757, 2021). "To the best of our knowledge, we firstly described considerable elevation of IL-6, IL-8, TNF-α, IP-10, HCC-1, and PF-4 levels in OSCC compared to OL patients, being detectable from early cancer stages." (PMID 33924500, 2021). "The KEGG pathway analysis indicated that the genes were mainly involved in pathways in cancer, Rap1 signalling pathway, PI3K-Akt signalling pathway, and TNF signalling pathway." (PMID 34762649, 2021). "Since CXCL9 and CCL3 are IFN-γ-related chemokines, here we focused on studying the anti-cancer effects of IFN-γ and TNF-α." (PMID 33175182, 2021). "KEGG analysis of core targets showed that AR treatment of CRF involved a variety of signaling pathways related to tumors: pathways in cancer, AGE-RAGE, IL-17, TNF, Toll-like receptor, and HIF-1 pathways." (PMID 34925533, 2021). "The most known cytokines to induce T cell dysfunction are IL-10, IL-6 and TNF-α, while TGF-β role in cancer is mostly related to epithelial-to-mesenchymal transition (EMT), invasion and metastasis in melanoma, breast and lung cancer." (PMID 33466674, 2021). "The core herbal prescription mainly intervenes in neuroactive ligand-receptor interaction, calcium signaling pathway, pathways in cancer, cGMP-PKG signaling pathway, and TNF signaling pathway." (PMID 34725557, 2021). "Another example is EV miRNA-7 derived from tumor necrosis factor (TNF)-like weak inducer of apoptosis (TWEAK)-stimulated macrophages, which inhibits cancer metastasis after transfer to EOC cells." (PMID 34552067, 2021). "Pro-inflammatory cytokines, such as interleukin (IL)-6, IL-1β, and tumor necrosis factor-α (TNF-α), promote cancer progression." (PMID 34833849, 2021). "Previously, tumor necrosis factor-α (TNF-α), a critical inflammatory mediator, was demonstrated to be a potential therapeutic target in numerous cancers." (PMID 34948424, 2021). "Obese adipose tissue increases TNF-α and IL-6 to promote insulin resistance, insulin and IGF-1 to facilitate cancer cell proliferation." (PMID 34034721, 2021). "In addition, intracellular iron protects cancer cells against natural killer (NK) cells and it has also been demonstrated that the heavy chain of the iron-storing protein ferritin inhibits apoptosis induced by tumor necrosis factor alpha (TNFα) through the suppression of ROS accumulation." (PMID 33815364, 2021).
cancer (continued). "We contribute to highlight the cooperation between TAM and NK cells through the secretion of IL-1β, TNF-α and IFN-γ, leading to the production of CCL22 by cancer cells." (PMID 33924428, 2021). "In the co-expression network of top 20 KEGG pathways enriched in hemolymph specifically expressed genes (brown module genes), the apoptotic pathways were interconnected with NF-kappa B signaling, TNF signaling, NOD-like receptor signaling, and cancer pathways." (PMID 33487168, 2021). "Another study with a mouse cancer model simulating the anatomical and functional features found in human oral cancer patients demonstrated that anti-NGF treatment decreased plasma TNF-α and IL-6 levels." (PMID 35053150, 2021). "The duality of TNF stimulation makes TAK1 a key target in mediating between growth and apoptosis in cancer cells." (PMID 32523651, 2020). "In murine models of cancer cachexia, the secretion of pro-inflammatory cytokines by WAT, such as TNFα and IL-6, has been observed." (PMID 32660156, 2020). "Since cytokines such as TNF can influence the expression and/or activity of Bcl-2 and caspase 3, circulating chemokine/cytokine-mediated changes in pro-apoptotic and anti-apoptotic proteins in skeletal muscle could have a profound impact on skeletal muscle function in cancer patients." (PMID 31941005, 2020). "M1 macrophages have a pro-inflammatory function and an antitumoral activity through the secretion of pro-inflammatory cytokines, such as TNF and interleukin (IL)-2, and the stimulation of CTL response against cancer cells." (PMID 33322132, 2020). "Conversely, the prevalence of macrophages with M1-like phenotypes expressing IL-12, Tumor Necrosis Factor alpha (TNF-alpha), and Nitric Oxide Synthase 2 (NOS2) has been reported to correlate with favorable clinical outcomes in many human cancers." (PMID 33374253, 2020). "Tumour necrosis factor alpha (TNF-α) is a cytokine secreted during inflammatory process accompanying RTH and the development of cancer itself." (PMID 31076897, 2020). "In this positive loop which is known as a vicious cycle, cancer cells can augment osteoclast generation and activation directly by producing osteoclastogenic factors including RANKL, tumor necrosis factor (TNF)-α, IL-1, IL-6, and IL-11." (PMID 33050237, 2020). "The results of KEGG pathway analysis showed that these genes involved in four significant cancer-related pathways, such as RNA transport, MAPK signaling pathway, transcriptional misregulation in cancer, and TNF signaling pathway." (PMID 33193600, 2020). "A series of experiments in murine cancer models have suggested that TNF-α KO mice are resistant to chemically induced carcinogenesis of the skin, and that inhibition of stromal cell TNF-α production decreases the incidence of liver tumors." (PMID 33005103, 2020). "For example, ROS can induce NF-κB activation which in turn promotes biosynthesis of COX, NO, and TNF-α and, therefore, scavenging ROS by EGCG would lead to its anti-cancer effects." (PMID 33027981, 2020). "Upregulation of TNFα, MCP-1 and IL-10 has been consistently observed in this study and in previous in vitro and in vivo models of cancer following IgE immunotherapy." (PMID 33203088, 2020). "TNF-α is a multifunctional cytokine that promotes EMT by activating AKT and NF-κB, resulting in augmented invasion and metastasis in many cancers, including OSCC cells." (PMID 32961679, 2020). "The model includes the densities of cancer cells (C), dendritic cells (D) and CTL cells (T), the concentrations of cytokines TNF-α and IL-12, and the proteins PD-1, PD-L1, TIM-3 and Gal-9." (PMID 32310956, 2020).